CATSPERH (catsper channel auxiliary subunit eta)
Description:
Auxiliary component of the CatSper complex, a complex involved in sperm cell hyperactivation.
Synonyms: TMEM262
Tractability: Antibody: UniProt predicts a signal peptide or a membrane-spanning region; its Gene Ontology location is reachable by antibodies, with medium confidence.
Gene: Protein-coding gene on chromosome 11 (65,084,979 to 65,089,375, reverse strand). Ensembl gene ENSG00000187066.
Subcellular location: Cell projection, cilium, flagellum membrane
Gene Ontology:
Molecular function: protein binding
Biological process: flagellated sperm motility; sperm capacitation; spermatogenesis
Cellular component: CatSper complex; sperm principal piece
Genetic constraint (gnomAD): Loss-of-function variants: 12 observed, 11.3 expected, observed/expected ratio (o/e) 1.06, 90% interval 0.68 to 1.68. The upper end of that interval is the gene's LOEUF score, 1.68, which puts it in group 6 of 6, group 1 being the genes least tolerant of losing a copy. Missense variants: 132 observed, 159.42 expected, observed/expected ratio (o/e) 0.83, 90% interval 0.72 to 0.96. Synonymous variants: 54 observed, 59.26 expected, observed/expected ratio (o/e) 0.91, 90% interval 0.73 to 1.14.
Homologues: Orthologues: chimpanzee TMEM262 (99% identical), macaque TMEM262 (91% identical), dog TMEM262 (78% identical), rabbit TMEM262 (78% identical), pig TMEM262 (76% identical), rat Tmem262 (72% identical), mouse Tmem262 (72% identical), guinea pig TMEM262 (63% identical).
Diseases named in the same sentence as CATSPERH in open-access papers:
CATSPERH is named in the same sentence as 1 disease in open-access papers, as found by Europe PMC text mining. Sharing a sentence is not in itself a finding about the gene and the disease.
CATSPERH shares sentences with these, for which no sentence is quoted: skeletal dysplasia (1 paper).